SFRP5 (secreted frizzled related protein 5)
Diseases named in the same sentence as SFRP5 in open-access papers (continued):
Sharing a sentence is not in itself a finding about the gene and the disease.
Obesity (continued). "The anti-inflammatory adipocytokine Sfrp5 modulates metabolic dysfunction during obesity in mice, and a2ml (Alpha2 macroglobulin-like) was shown to be essential for liver development in zebrafish." (PMID 28993314, 2017). "Serum SFRP5 level of diabetic patients with obesity is lower than normal subjects, while GLP-1 agonist liraglutide intervention results in weight loss and serum SFRP5 elevation." (PMID 28824700, 2017). "Delivery of SFRP5 via adenovirus alleviated glucose intolerance and hepatic steatosis in mice with diet-induced obesity." (PMID 28824700, 2017). "This study supports a role in which SFRP5 inhibits Wnt signaling and consequently suppresses oxidative metabolism and stimulate adipose growth during obesity." (PMID 28796178, 2017). "We propose that an explanation for some of the DIO variability in this obesity model is that developmental phases affect the expression and function of important adipose biofunctional markers such as Mest, Sfrp5, Scl25a1, and Scd1 in white fat depots." (PMID 28400497, 2017). "Based on its role in obesity and inflammation, we expect that SFRP5 exerts anti-inflammatory effect in obesity related lung injury." (PMID 24899788, 2014). "Future clinical studies are required to determine the role of adipose SFRP5 in the control of obesity-related abnormalities in glucose homeostasis and insulin sensitivity." (PMID 24733068, 2014). "We next measured wnt5a and sFRP5 protein concentrations in serum samples of n = 12 lean control subjects and n = 23 subjects with obesity." (PMID 22384249, 2012). "In the same study two independent mouse models of obesity exhibited reduced sFRP5 expressions and an increased wnt5a/sFRP5 ratio in adipose tissue suggesting these two bioactive molecules to be involved in the development of obesity and type 2 diabetes." (PMID 22384249, 2012). "In diet induced obesity, sFRP5 expression in adipose tissue was found to be up-regulated in animal models." (PMID 22384249, 2012). "The function of Wnt signaling in diet-induced obesity is likely to be different, since SFRP5 is predominantly expressed in the mature adipocyte and Naked1 is expressed in both the mature adipocyte and stromal-vascular fractions." (PMID 16733553, 2006). "Furthermore, the exclusion of children and adolescents with chronic or acute disease offered us the opportunity to gain insight into the role of Sfrp5 in the initial periods of the pathophysiology of obesity." (PMID 39339733, 2024). "Research has been performed elucidating Sfrp5’s role in obesity." (PMID 39339733, 2024). "It is likely that the selection of the study population in previous studies (mainly children with obesity), could explain why the increased Sfrp5 concentrations were noted only in the morbid obesity subgroup." (PMID 39339733, 2024). "The decrease in circulating SFRP5 levels may serve as an indication that the clearance function of SFRP5 during the obesity stage can still be compensated." (PMID 37645520, 2023). "Since obesity has been suggested to induce SFRP5 expression in mice and humans, we hypothesize that NAFLD may result in the same effect by increasing metabolic imbalance." (PMID 36077270, 2022). "Sfrp5 expression was reduced in AT in mouse models of obesity and T2DM." (PMID 35909571, 2022). "SFRP5 is a vital adipokine that could mediate the crosstalk between obesity and BC metastasis and new therapy by promoting SFRP5 expression in the adipose microenvironment might be an effective way in preventing BC metastasis." (PMID 34350120, 2021). "Taken together, these results suggest that Sfrp5 regulation is related to obesity." (PMID 34371968, 2021). "In addition, they detected reduced SFRP5 level in the obesity-induced hypertrophic adipocyte model, and the hypertrophic adipocytes augment BC cell invasion and migration through inhibiting SFRP5 expression." (PMID 34350120, 2021).
Obesity (continued). "Many factors may affect the secretion of SFRP5, such as the extent of obesity, glycemic status, medications, and other diseases and complications." (PMID 34184187, 2021). "SFRP5 is a novel adipokine with anti-inflammatory properties and is related to obesity." (PMID 34350120, 2021). "Therefore, Sfrp5 plays a pivotal role in the metabolic complications of obesity by inhibiting Wnt5a and the inflammation that the latter promotes." (PMID 34371968, 2021). "Regarding animal models, previous studies reported that SFRP5 is a protective adipokine for glucose tolerance, adipose inflammation, hepatic steatosis, and fibrosis, and its anti-inflammatory role is perturbed in animal models of obesity with T2DM." (PMID 34198988, 2021). "Similarly, cross-sectional studies showed that Sfrp5 is negatively correlated with indices of obesity, such as BMI, waist-to-hip ratio (WHR), percent body fat, glycolipid metabolism and inflammation." (PMID 34371968, 2021). "Despite the augmented expression of SFRP5 in adipose tissues, it seems to decline following the aggravation of metabolic dysfunction, considering the transient upregulation of SFRP5 with milder inflammation in adipocytes and ensuing drop after the development of obesity." (PMID 34948320, 2021). "Sfrp5 is an adipokine which may play a protective role against obesity-related insulin resistance and T2D by binding to Wnt5a and improving insulin sensitivity." (PMID 34371968, 2021). "SFRP5 over-expression via adenovirus could alleviate obesity, adipose inflammation, and hepatosteatosis." (PMID 32982804, 2020). "Other studies are necessary to clarify the role of SFRP5 in obesity and metabolic syndrome." (PMID 33192583, 2020). "Our review might stimulate future research using SFRP5 as a promising novel therapeutic target for the treatment of obesity, T2DM and CHD." (PMID 32004418, 2020). "Serum SFRP5 levels are low in subjects with obesity and T2DM." (PMID 31208019, 2019). "In conclusion, RAL ameliorated estrogen deficiency-induced obesity, adipogenesis, and adipose tissue hypertrophy as well as inflammation via distinct activation of canonical Wnt10b/β-catenin and non-canonical SFRP5 signaling." (PMID 31470850, 2019). "In addition, Sfrp5 can be used as a candidate target for studying the anti-obesity mechanism of Sal B, and its specific mechanism should be the emphasis of future research." (PMID 30842902, 2019). "As an anti-inflammatory adipokine, Sfrp5 inhibits the accumulation of activated macrophages in adipose tissue via noncanonical regulation of the JNK signaling pathway to ameliorate glucose intolerance in mouse models of obesity and T2DM." (PMID 30120048, 2019). "Their results also suggested that a failure to upregulate SFRP5 in obesity may lead to unrestrained pro-inflammatory actions of Wnt-5A, resulting in metabolic dysfunction." (PMID 30704061, 2019). "Similar report also indicated that SFRP5 expression was reduced in rodents with genetic or dietary obesity, while systemic administration of SFRP5 improved glucose tolerance and insulin resistance through inhibition of inflammatory responses and Wnt5a-JNK signaling." (PMID 31470850, 2019). "As an anti-inflammatory adipokine, SFRP5 could be negatively modulated in the development of obesity, contributing to an unfavorable metabolic phenotype." (PMID 29789397, 2018). "This highlights the crucial role of SFRP5 in the pathogenesis of obesity and T2DM." (PMID 29789397, 2018). "Sfrp5 stimulates adipocyte growth during obesity by inhibition of Wnt signaling." (PMID 29507687, 2018). "Data from mouse studies reported that Sfrp5 levels depended on the duration of obesity." (PMID 28851362, 2017). "SFRP5 knockout mice develop obesity and adipose inflammation, while SFRP5 overexpression via adenovirus could alleviate obesity, adipose inflammation and hepatosteatosis." (PMID 28824700, 2017).
Obesity (continued). "However, it has been demonstrated that, in the setting of obesity, SFRP5 secretion by adipocytes exerts salutary effects on metabolic dysfunction by controlling inflammatory cells within adipose tissue." (PMID 25922847, 2015). "This suggests that a subgroup of individuals with obesity and T2D are characterized by additional alterations in lipid metabolism, which may be reflected or mediated by adipokines including SFRP5, RBP4, CTRP3 and 5, omentin and adiponectin." (PMID 24968098, 2014). "Another contradicted study also showed increased SFRP5 expression in diet-induced obesity." (PMID 24899788, 2014). "Until now data on wnt5a and sFRP5 in human subjects with obesity are limited." (PMID 22384249, 2012). "Therefore, it is speculated that Sfrp5 possibly contributes to the pathophysiology of obesity and its complications." (PMID 39339733, 2024). "Furthermore, Sfrp5 expression levels in animal studies were dependent on the duration of obesity." (PMID 39339733, 2024). "Moreover, they noted that after 24 weeks of nourishing a high-fat/high-sucrose diet for wild-type mice, leptin deficiency mice (ob/ob) and Zucker diabetic fatty mice (fa/fa) resulted in obesity phenotype, down-regulation of SFRP5 expression, and overexpression of WNT5A." (PMID 37542207, 2023). "Hence, SFRP5 is a crucial protein at the intersection between obesity, dyslipidemia, and T2DM." (PMID 37542207, 2023). "Therefore, we hypothesize that SFRP5/WNT5A pathway in adipose tissue might play an important role in NAFLD-related to obesity pathogenesis through the adipose tissue-liver axis." (PMID 36077270, 2022). "Therefore, the aim of this study was to assess serum SFRP5 concentration in a young healthy population in relation to insulin sensitivity and obesity and its regulation by hyperinsulinemia and/or serum free fatty acids (FFA) elevation to evaluate the link between SFRP5 and insulin sensitivity." (PMID 34184187, 2021). "Therefore, it is hypothesized that Sfrp5 and Wnt5a may also be involved in the pathogenesis of obesity and obesity-related disorders." (PMID 34371968, 2021). "Obesity is a very complex abnormal state, accompanied by various physiological and molecular alterations, which involves the complicated roles of adipokines (leptin, adiponectin, resistin, visfatin, and SFRP5), insulin, IGF, sex hormone, and chronic inflammation." (PMID 34350120, 2021). "Therefore, we propose that SFRP5, as an anti‐inflammatory adipokine, might link obesity, T2DM to CHD." (PMID 32004418, 2020). "Therefore, we propose that SFRP5 may exert a protective role in the pathogenesis of adipose tissue inflammation and obesity via non‐canonical WNT5A signalling pathway." (PMID 32004418, 2020). "Further studies are necessary to investigate the impact of Sfrp5 on insulin secretion in isolated islets and/or primary beta cells from rats and humans and to evaluate whether Sfrp5 might be of therapeutic interest for the treatment of obesity and diabetes." (PMID 30921355, 2019). "Further elucidation into whether SFRP5 levels are regulated during the development and progression of obesity and diabetes mellitus is required, since there remain elements of controversy as to whether they increase all the time or fall below at particular point, thereby influencing metabolism." (PMID 29789397, 2018). "So far, it is not known whether SFRP5 plays a physiological role as mediator between BMI and obesity-associated comorbidities or between weight loss and an improved cardiometabolic risk profile." (PMID 28851362, 2017). "Furthermore, Sfrp5 gene expression in adipose tissue was unaffected by obesity." (PMID 24465779, 2014). "In addition, the high correlations between SFRP5, Naked1, and MEST in inguinal fat depots suggest a mechanism of coordinated regulation of the expression of these genes in association with susceptibility to diet-induced obesity." (PMID 16733553, 2006).
Obesity (continued). "Emerging research has consistently shown decreased circulating levels of SFRP5 and increased levels of Wnt5a in patients with CAD and obesity when compared to healthy controls." (PMID 37645520, 2023). "To conclude, we reported increased SFRP5 mRNA expression in SAT and VAT of NAFLD-related to obesity subjects, suggesting an implication of the SFRP5-WNT5A pathway in NAFLD pathogenesis, probably due to the adipose tissue-liver axis." (PMID 36077270, 2022). "In this study, our cohort of women made it possible to relate SFRP5, WNT5A and PPARγ mRNA abundance in SAT and VAT with obesity and NAFLD." (PMID 36077270, 2022). "Next, we wanted to evaluate the mRNA abundance of SFRP5, WNT5A and PPARγ and their link with obesity, so we classified the cohort into NW subjects (control group) and MO patients." (PMID 36077270, 2022). "Secreted frizzled-related protein 5 (SFRP5) is considered to be a tumor suppressor gene and its circulating level is a feature in obesity-related metabolic disorders." (PMID 35701840, 2022). "Additional human studies will be required to shed light on the influence of Wnt5a/Sfrp5 in NAFLD and hepatic fibrosis observed in obesity." (PMID 34371968, 2021). "In addition to studies using obesity animal model, the ratio of plasma Wnt5a/SFRP5 in obese patients is considered to be a more accurate evaluation index, which indicates that the decrease of SFRP5 concentration may be a direct factor leading to cardiovascular disease in obese patients." (PMID 34489867, 2021). "Moreover, the influence of obesity on circulating SFRP5 remains unclear too." (PMID 34184187, 2021). "Furthermore, we discussed how SFRP5 may represent a novel link between obesity, T2DM and CHD." (PMID 32004418, 2020). "We selected four DEmRNAs (Wbscr27, Sfrp5, Adig, and Saa3), DEcircRNAs- chr7:67264864–67268400:- and DElncRNA-ENSMUST00000169194, which are most relevant to obesity, for use in verifying RNA-seq results using qRT-PCR." (PMID 30842902, 2019). "As SFRP5 does reduce production of proinflammatory TNFα, IL-6, and MCP-1, we expect it to exert anti-inflammatory effect in obesity related lung injury." (PMID 24899788, 2014). "With the availability of the recombinant SFRP5, more preclinical and clinical trials were needed to explore the effect of SFRP5 on OILI, as well as other comorbidities of obesity." (PMID 24899788, 2014). "A possible role of a novel adipocyte-secreted hormone, named secreted frizzled-related protein 5 (SFRP5), has been shown to link obesity with diabetes in animal studies." (PMID 24362411, 2014). "Some groups have seen Sfrp5 expression increase with obesity and when Sfrp5 expression is lost there is protective effect against diet induced obesity (DIO), while others have observed that elimination of Sfrp5 exacerbates obesity and insulin resistance." (PMID 24339864, 2013). "Furthermore, serum Sfrp5 concentrations in subjects with coronary artery disease (CAD) and adults with obesity were inversely related to hs-CRP concentrations." (PMID 39339733, 2024). "In addition, Pip treatment can prevent obesity and improve lipid metabolism by regulating adipose tissue expansion (ATE) related genes Sfrp5, MEST, PTRF/Cavin1." (PMID 38547097, 2024). "We aimed to evaluate the role of the SFRP5-wingless-MMTV integration site family member 5a (WNT5A) pathway, closely related to adipogenesis, in subcutaneous (SAT) and visceral adipose tissues (VAT) and its relationship with obesity-related NAFLD." (PMID 36077270, 2022). "In this study, SFRP5 levels were negatively associated with incidence of PCOS, HA, IR and inflammation independent of obesity." (PMID 34284806, 2021). "Consistent with the findings of Almario and other study, serum SFRP5 level was independent of obesity." (PMID 34284806, 2021).
Obesity (continued). "In response to obesity and T2DM, it was found that the plasma levels of SFRP5 were significantly lower in Chinese obese individuals as well as T2DM subjects compared with normal subjects, in which SFRP5 was an independent factor influencing glucolipid metabolism, inflammation, and IR." (PMID 29789397, 2018). "This may suggest that under conditions of T2D and obesity, adiponectin, omentin, CTRP3 and 5, RBP4 and SFRP5 reflect additional alterations in lipid metabolism." (PMID 24968098, 2014). "The results indicate that SFRP5, MEST, and BMP3, but not Naked1, are positively associated with the subsequent development of diet-induced obesity in 16 wk-old mice." (PMID 16733553, 2006). "Similarly, among the 15 anti-inflammatory organokines, 7 (adiponectin, Omentin-1, ZAG, SFRP5, CTRP3, IL-10, and DEL-1) showed reduced levels and 8 (LCN2, VASPIN, IL-1RA, FGF21, GDF15, MANF, Irisin, and IL-6) showed elevated levels in patients with obesity." (PMID 35909571, 2022). "In 3 T3-L1 preadipocytes, demethylation did not increase leptin gene expression, and the diet-induced up-regulation of leptin, Mest/Peg1, and sFRP5 gene expression in white adipose tissue (WAT) during the development of obesity in mice is not mediated directly by changes in DNA methylation." (PMID 33736593, 2021). "WNT5a induces the non-canonical activation of JNK1, and SFRP5 deficient mice show highly activated JNK1 in HFD indicating that SFRP5 inhibits WNT5a mediated non-canonical JNK1 activation in adipose tissues to suppress obesity-induced inflammation and insulin resistance." (PMID 23781214, 2013). "Our study demonstrates the robust downregulation of circulating SFRP5 levels in both heart failure and CAD, independent of obesity and diabetes." (PMID 37504530, 2023). "Rats not expressing Sfrp5 show proliferation of pancreatic β-cells via IGFBP-3, an insulin-compensatory lesion observed in obesity." (PMID 34371968, 2021). "Plasma SFRP5 levels were decreased in PCOS (odds ratio: 0.78, 95% confidence interval (CI):0.703–0.866, P < 0.001) independent of obesity." (PMID 34284806, 2021). "In obesity it has been observed that mRNA levels of SFRP1-4, but not SFRP5, were altered; finding that SFRP1, SFRP2 and SFRP4 are adipokines and their expressions correlated with insulin sensitivity." (PMID 25922847, 2015).